RN7SL144P (RNA, 7SL, cytoplasmic 144, pseudogene)
Gene: Miscellaneous RNA gene on chromosome X (41,683,168 to 41,683,462, reverse strand). Ensembl gene ENSG00000242559.
Homologues: Orthologues: chimpanzee Metazoa_SRP (99% identical). Paralogues in human: RN7SL1 (84% identical), RN7SL2 (84% identical), RN7SL3 (83% identical), RN7SL326P (80% identical), RN7SL122P (80% identical), RN7SL230P (80% identical), RN7SL296P (80% identical), RN7SL239P (79% identical), RN7SL566P (79% identical), RN7SL7P (79% identical), RN7SL127P (79% identical), RN7SL556P (79% identical), and 705 more.